TMLHE (trimethyllysine hydroxylase, epsilon)
Description:
Converts trimethyllysine (TML) into hydroxytrimethyllysine (HTML) in the carnitine biosynthesis pathway. [Isoform 2]: Lacks trimethyllysine dioxygenase activity. [Isoform 3]: Lacks trimethyllysine dioxygenase activity. [Isoform 4]: Lacks trimethyllysine dioxygenase activity. [Isoform 5]: Lacks trimethyllysine dioxygenase activity.
Synonyms: TMLD; TMLH; FLJ10727; BBOX2; XAP130; AUTSX6; TMLHED
Tractability: PROTAC: ubiquitination databases record sites on it; its protein half-life has been measured.
Gene: Protein-coding gene on chromosome X (155,488,606 to 155,719,107, reverse strand). Ensembl gene ENSG00000185973.
Subcellular location: Mitochondrion matrix
Subcellular location (Human Protein Atlas): Mitochondria
Pathways (Reactome):
Metabolism: Carnitine synthesis
Gene Ontology:
Molecular function: trimethyllysine dioxygenase activity; iron ion binding; oxidoreductase activity
Biological process: carnitine biosynthetic process
Cellular component: mitochondrial matrix; mitochondrion
Gene-disease validity (ClinGen):
ClinGen rates the evidence that TMLHE causes each of these diseases.
autism spectrum disorder (X-linked): Disputed. A spectrum of developmental disorders that includes autism, and Asperger syndrome.
Homologues: Orthologues: chimpanzee TMLHE (100% identical), macaque TMLHE (99% identical), pig TMLHE (92% identical), rabbit TMLHE (92% identical), dog TMLHE (87% identical), rat Tmlhe (70% identical), tropical clawed frog tmlhe (70% identical), zebrafish tmlhe (67% identical), guinea pig TMLHE (64% identical), Caenorhabditis elegans gbh-2 (31% identical), Drosophila melanogaster Tmlh (30% identical). Paralogues in human: BBOX1 (25% identical).
Diseases named in the same sentence as TMLHE in open-access papers:
TMLHE is named in the same sentence as 15 diseases in open-access papers, as found by Europe PMC text mining. Sharing a sentence is not in itself a finding about the gene and the disease. The quoted sentences say what the papers report.
autism (11 papers, 2014 to 2024). Persistent deficits in social interaction and communication and interaction as well as a markedly restricted repertoire of activity and interest as well as repetitive patterns of behavior. "We previously analyzed the regulation and expression of the pseudoautosomal region 2 gene SPRY3, which is adjacent to X chromosome-linked TMLHE, a known autism susceptibility gene." (PMID 31275178, 2019). "TMLHE is the first enzyme in the carnitine biosynthesis pathway, and TMLHE deficiency causes regressive autism symptoms that can be improved via carnitine supplementation." (PMID 30945415, 2019). "The X-linked copy of SPRY3 is adjacent to a known autism gene, TMLHE, and a proportion of SPRY3 transcripts arise from upstream promoters in the X-linked F8A3 and TMLHE regions." (PMID 31275178, 2019). "TMLHE is an enzyme in the carnitine biosynthesis pathway, and carnitine deficiency is associated with autism." (PMID 31275178, 2019). "TMLHE exon 2 deletions were more frequent in probands from families with more than one affected male compared to control subjects suggesting that TMLD deficiency is a risk factor for autism with low penetrance (2–4%)." (PMID 31500110, 2019). "Deletions in TMLHE are relatively common (1/350 males), cause carriers to be auxotrophic for carnitine, and have also been linked to an increased probability of developing autism in boys." (PMID 39026322, 2024). "This could also explain the links between TMLHE deletions in males and autism, since TMLHE deficiency also results in increased TML and 5-AVAB levels." (PMID 39026322, 2024). "Detection of frequent inborn errors in the biosynthesis of carnitine from trimethyllysine, caused by a deficiency in the activity of the TMLHE gene, may help explain the reasons for dysmorphic autism." (PMID 33805796, 2021). "Mutations in TMLHE, an enzyme catalyzing the first step of carnitine biosynthesis, are relatively frequent among this class of diseases and are associated with developmental neuropsychiatric disorders, including increased risk of autism." (PMID 32185173, 2020). "TMLHE mutations are rare but well-established autism susceptibility factors." (PMID 31275178, 2019). "However, only about 3% of men with TMLHE gene deficiency developed autism." (PMID 33805796, 2021). "Deletion of the TMLHE gene, which is the first step in carnitine synthesis pathway and located on the X chromosome, is found more often in males with non-dysmorphic autism suggesting that TMLHE deficiency is a risk factor for autism, albeit with low penetrance (estimated at 2–4%)." (PMID 30581393, 2018). "The risk of nondysmorphic autism connected with TMLHE mutation may be diminished by appropriate carnitine supplementation during the early stages of child brain development." (PMID 33805796, 2021). "Deletion of the TMLHE gene, which is part of the carnitine synthesis pathway and located on the X chromosome, is found more often in male-male multiplex families with non-dysmorphic autism, suggesting that TMLHE deficiency is a risk factor for ASD, albeit with low penetrance (estimated at 2–4%)." (PMID 30995737, 2019). "It was suggested, however, that carnitine biosynthesis may be a risk factor for nondysmorphic autism as the TMLHE-deficient patient was identified in an autism spectrum disorder (ASD) cohort." (PMID 24986124, 2014). "TMLHE (conjugated with chromosome X), which codes trimethyllysine dioxygenase (TMLD), the first enzyme on the mitochondrial carnitine synthesis pathway, was detected in men with nondysmorphic autism (frequency 1 in 350 men)." (PMID 33805796, 2021).
autism spectrum disorder (2 papers, 2014 to 2023). "Deletion of exon 2 of the trimethyllysine hydroxylase epsilon (TMLHE) gene was identified in probands with autism spectrum disorder (ASD)." (PMID 37553674, 2023). "A search for genetic variants throughout the genome in individuals with autism spectrum disorder (ASD) and their families identified a novel deletion of exon 2 of the X-chromosomal trimethyllysine hydroxylase epsilon (TMLHE) gene." (PMID 37553674, 2023).
Anxiety (1 paper, 2023). Intense feelings of nervousness, tension, or panic often arise in response to interpersonal stresses. "Multiple high-confidence ASD risk genes associated with anxiety were dysregulated in our RNA-seq data including TMLHE and GRID2, DNAH10, GRIA1, SLC6A4, and IGF1." (PMID 37486945, 2023).
DOCK8 immunodeficiency syndrome (1 paper, 2023). "These genes are linked with a range of X-linked and autosomal disorders, e.g., TMLHE (X-linked Autism), CDKL5 (Developmental Encephalopathy), FANCD2 (Fanconi anaemia), FLT4 (congenital heart defects), FTCD (Glutamate formiminotransferase deficiency), and DOCK8 (DOCK8 immunodeficiency syndrome)." (PMID 38033082, 2023).
cancer (3 papers, 2022 to 2025). A tumor composed of atypical neoplastic, often pleomorphic cells that invade other tissues. "Then, risk scores were calculated for every cancer sample calculated by using the following formula: Riskraw = DAD1*2.316+CYCS*1.426+CSNK2A2*1.576+VPS25*0.728+VDAC1*0.976+TMLHE*0.381+CYTH3*0.024+PRKCA*0.260-TP73*0.567+FZD6*0.047+SQSTM1*0.094-MAP2K7*3.070." (PMID 35185897, 2022). "The FCGBP, F13A1, FRY, and TMLHE genes had significantly higher expression in normal tissues than in cancer (P = 2.8e-07, P = 3.3e-14, P < 2.22e-16 and P < 2.22e-16, respectively)." (PMID 40264151, 2025).
TMLHE also shares sentences with these, for which no sentence is quoted: carnitine deficiency (2 papers); cognitive decline (1); encephalitis (1); Fanconi anaemia (1); genetic disorders (1); Glutamate formiminotransferase deficiency (1); methylmalonic acidemia (1); ovarian carcinoma (1); tumor (1); viral infection (1).